METTL3 (methyltransferase 3, N6-adenosine-methyltransferase complex catalytic subunit)
Diseases named in the same sentence as METTL3 in open-access papers (continued):
Sharing a sentence is not in itself a finding about the gene and the disease.
cancer (continued). "Depletion of METTL3 impaired cancer proliferation and cancer metastasis in vitro and in vivo." (PMID 32126149, 2020). "If METTL3 is involved in the early stage of gastrointestinal cancer, it could improve early cancer diagnosis and prevention." (PMID 32429972, 2020). "The expression of METTL3 is dysregulated in cancer via different mechanisms." (PMID 32854717, 2020). "In cancer cells, MYC has been implicated as a key positive regulator of CAP-dependent mRNA translation, a process that was predicted to be downregulated upon Mettl3 ablation in embryonc skin." (PMID 32845239, 2020). "Therefore, from a therapeutic perspective, the mechanistic understanding of METTL3-induced cancer cell biological function and glucose metabolism in cellular regulation will enable the identification of the novel therapeutic targets." (PMID 32245489, 2020). "Furthermore, we showed that there is strong correlation between the METTL3/TGFβ1/Snail axis and cancer progression in lung metastasis potential cancer cell models." (PMID 31991845, 2020). "The expression of METTL3 in the normal nasopharyngeal mucosa and nasopharygeal carcinoma tissues." (PMID 32596151, 2020). "METTL3-METTL14-WTAP-mediated m6A modification is associated with cancer and the relationship between m6A and cancer has not been fully explored." (PMID 31226160, 2019). "METTL3, the first reported m6A reader, was identified as the main methyltransferase for the methylation process and was further proven to affect the development of many cancers." (PMID 31492150, 2019). "However, METTL3 can also modulate the cancer process by directly promoting the translation of oncogenes via interaction with the translation initiation machinery through recruitment of eukaryotic translation initiation factor 3 subunit h (eIF3h)." (PMID 31921660, 2019). "Consequently, different downstream targets of METTL3 and the dominant cancer-related pathways involved in the process bring about the discrepancy in cell fate of different tumors." (PMID 31921664, 2019). "Expression, clinical significance, and biological function of METTL3 in various cancers." (PMID 31921660, 2019). "However, further studies are still needed to clarify the exact details of METTL3 expression, roles, and mechanisms in human cancers." (PMID 31921660, 2019). "AML is one of the cancers with the highest expression of both METTL3 and METTL14." (PMID 31024852, 2019). "METTL3 is dysregulated and plays a dual role in various types of human cancers." (PMID 31921660, 2019). "The precise molecular mechanisms underlying the role of METTL3 in cancer initiation and progression are not thoroughly understood and require further systematic investigation." (PMID 31921660, 2019). "The expression and pro- or anticancer role of METTL3 in different cancers remain controversial." (PMID 31921660, 2019). "METTL3 can also regulate cancer-related gene expression via m6A modification." (PMID 31921660, 2019). "Given its effects on inflammation, cancer, and immune regulation, we hypothesize that METTL3 may affect the development and progression of RA by regulating macrophage-mediated inflammation." (PMID 31772500, 2019). "Moreover, METTL3 depletion enhanced chemo- and radiosensitivity of cancer cells, which suggests that METTL3 has an important role in the acquisition of resistance to anticancer drugs and irradiation." (PMID 30149601, 2018). "METTL3 also directly promotes translation of certain mRNA in human cancer cells by recruiting eIF3." (PMID 30062093, 2018). "One example is that METTL3 modulates nn n zSP1, an oncogene in several cancers which regulates c-MYC expression in this way, identifying a new paradigm for selecting RNAs to be modified, namely the stable recruitment of the RNA-modifying enzyme to specific genomic loci." (PMID 29587823, 2018). "In addition to methyltransferase activity, METTL3 also influences cancers indenpendently of its catalytic subunit." (PMID 30062093, 2018).
cancer (continued). "METTL3, as a methyltransferase, exhibits oncogenic properties by depositing m6A modifications on critical transcripts, promoting the development and progression of various cancers, including hematologic malignancies and solid tumors, and holds potential for cancer therapy." (PMID 39980152, 2025). "Targeting METTL3 could present new avenues for cancer immunotherapies." (PMID 39802639, 2025). "It indicated that METTL3 could negatively regulate the expression of GATA3 in cancer cells." (PMID 39800682, 2025). "Furthermore, clinical studies have shown a strong correlation between the cytoplasmic localization of METTL3 and GC progression, suggesting that METTL3’s subcellular distribution may serve as a prognostic marker for cancer patients." (PMID 40271153, 2025). "Moreover, combining FDA‐approved HDAC6 inhibitors currently under clinical investigation with METTL3 inhibitors may offer a promising treatment strategy for cancers characterized by ciliary disorders, potentialy expanding therapeutic options." (PMID 39535388, 2025). "Overexpression of E2F5, even when METTL3 is knocked down, could promote cancer growth." (PMID 40448344, 2025). "METTL3 inhibitors may have the potential to enhance the efficacy of cancer therapies." (PMID 40675967, 2025). "However, the mechanism by which METTL3 promotes carcinogenesis may differ across various cancer types." (PMID 39054967, 2024). "The thematic map showed that METTL3, plant viruses, cancer progression and type I interferon (IFN-I) reflected a good development trend and might become a research hotspot in the future, while post-transcriptional modification, as an emerging or declining theme, might not develop well." (PMID 38238848, 2024). "In addition, screening or designing novel small molecular inhibitors utilizing artificial intelligence (AI) techniques and developing other targeting strategies such as targeted protein degradation may open new avenues for targeting METTL3 in cancer therapy." (PMID 38322265, 2024). "As a result, we found that METTL3 deficiency may also sensitize HNSCC cells to cisplatin by more effective cell cycle arrest, apoptosis induction, and inhibition of colony formation and, in contrast, increased the expression of cancer stem cell markers." (PMID 38966069, 2024). "In addition, certain LLPS behaviors of METTL3 cancer mutants have now been observed." (PMID 39006762, 2024). "However, the functional mechanisms of METTL3 in LUAD might be complex due to the double-sided effects of METTL3 in different cancers, but in depth exploration of novel regulatory mechanisms of METTL3 in LUAD is urgently needed." (PMID 39095708, 2024). "Consequently, METTL3 depletion sensitizes cancer cells to DNA damage-based therapies." (PMID 39085650, 2024). "Finally, we found that METTL3 may constitute a significant player in the acquisition of stemness potential by cancer cells." (PMID 38966069, 2024). "Moreover, METTL3 was found highly expressed in carcinoma tissues compared with adjacent." (PMID 38764726, 2024). "Overcoming MHC-I downregulation by targeting METTL3, or similar RNA-modifying enzymes, may potentiate other T-cell-based cancer therapies, including CAR-T and adoptive T-cell transfer, and it might also be useful for stimulating T-cell responses in chronic viral infections." (PMID 38072988, 2023). "After Alarcon's research concerning METTL3 and m6A set a research foundation and reference for m6A‐dependent miRNAs processing, accumulating studies have been conducted and showed that writer‐mediated miRNAs maturation exhibited generality of aggressive phenotypes in various cancers." (PMID 36162823, 2023). "Therefore, the expression of VEGFA in METTL3-silenced cancer cells was investigated." (PMID 38001065, 2023). "Additionally, the role of METTL3 in regulating cancer cell migration was investigated." (PMID 38001065, 2023).
cancer (continued). "According to reports, the m6A “writer” proteins methyltransferase-like 3 (METTL3) and METTL14, as well as the “eraser” protein obesity-associated protein (FTO), are intricately involved in the modulation of m6A methylation and the development of various cancer types." (PMID 37938417, 2023). "Furthermore, the discovery of new HR factors in cancer, such as METTL3, may broaden PARPi therapeutic potential." (PMID 39872957, 2023). "However, given that METTL3 could facilitate cancer progression through an anchoring effect in a non-m6A modification manner, there are still unknown mechanisms in the METTL3 regulatory role in GI carcinogenesis." (PMID 37965577, 2023). "Importantly, the inhibitory effect of METTL3 silencing on cancer could be reversed to some extent by ANGPTL3 inhibition." (PMID 37344779, 2023). "Therefore, F. nucleatum could induce epigenetic modifications in the KIF26B gene at transcriptional level through the YAP/FOXD3/METTL3 axis, ultimately facilitating the invasiveness of cancer cells." (PMID 38023192, 2023). "The investigators found that low expression of Mettl3 may facilitate OC cell apoptosis through the mitochondrial apoptotic pathway and inhibit cancer cell invasion by reducing activation of the AKT signaling pathway and the expression of the downstream effector Cyclin D1." (PMID 37007040, 2023). "However, in several other cancer cell types, METTL3 was shown to promote cell proliferation." (PMID 35350378, 2022). "Therefore, METTL3 can be a new treatment target for cancers." (PMID 35012593, 2022). "In addition, silencing METTL3 could significantly promote cell proliferation and migration and induce G0/G1 arrest in some cancers." (PMID 36090276, 2022). "Therefore, all these data further confirmed that METTL3 might exist as a critical oncogene that promoted cancer progression." (PMID 35794583, 2022). "However, other studies reported that some cancers were related to the high expression of METTL3 and increased m6A methylation, which might involve different mechanisms and require more in-depth and detailed studies." (PMID 36371254, 2022). "In addition, METTL3 exerts pro-cancer effects in tumors and is also specifically regulated by miRs." (PMID 35892080, 2022). "Thus, METTL3 may be a therapeutic target in cancer treatment for inhibiting EMT and the metastasis of cancers." (PMID 36614956, 2022). "Moreover, METTL3 and METTL14 show completely contrary effects on cancer progression, indicating that METTL3 and METTL14 may have some biological functions that are independent of m6A modification, which deserves further study." (PMID 36347025, 2022). "In cancers of the female reproductive system, decreased methylation of m6A has been found in endometrial cancer, which may be associated with METTL14 mutation or decreased expression of METTL3." (PMID 34794452, 2021). "Moreover, METTL3 could increase the expression of HBXIP, thus forming a positive feedback loop of HBXIP/let-7g/METTL3/HBXIP to accelerate cancer cell proliferation." (PMID 34345203, 2021). "Moreover, both MTA1 and METTL3 are realized to accelerate cancer metastasis." (PMID 33435156, 2021). "Genetic alterations of METTL3 could promote growth of cancer cells." (PMID 34514103, 2021). "Could METTL3 increase sensitivity of other chemotherapeutic drugs in cancer patients?" (PMID 34514103, 2021). "However, the sorafenib resistance owed to the enhanced autophagy process which acted as a protective mechanism in cancer and could be induced by METTL3 silencing." (PMID 34046411, 2021). "METTL3 could promote m6A mRNA methylation of pri-miRNA in human cancers based on previous evidence." (PMID 33420414, 2021). "That said, whether METTL3 is cancer-inhibiting or cancer-promoting remains controversial." (PMID 34794452, 2021).
cancer (continued). "Notably, these studies were limited to UVC radiation and cancer cell lines, and therefore future studies into the role of METTL3-mediated m6A in UVA and UVB responses in relevant skin models will further elucidate these potential connections to skin cancer pathology." (PMID 34298617, 2021). "METTL3 has been found to be upregulated with increased m6A levels in cancer compared with those in normal tissues, suggesting a potential oncogenic role in different cancer types including AML, renal cell carcinoma, non-small cell lung cancer (NSCLC) and gastric cancer." (PMID 33879235, 2021). "Whether METTL3 regulates cancer stemness in other gastrointestinal cancers deserves further study." (PMID 32429972, 2020). "In multiple human cancer cell lines, a fraction of METTL3 protein has been observed in the cytoplasm at various proportions and the possible reasons could be due to varied amounts of protein abundance ratios between METTL3 and METTL14 with other adaptor subunits." (PMID 33330128, 2020). "Inhibiting METTL3/14 may be a novel strategy for the treatment of malignant myeloid tumours." (PMID 33029866, 2020). "Therefore, METTL3 was identified as a suppressor or promoter in certain cancers and further studies have indicated that the m6A level was changing following the development of cancer, which may partly explain the contradiction." (PMID 33552994, 2020). "In summary, we make a compelling illustration that the overexpressed METTL3 in BCa, the major methyltransferase catalysing m6A modification of mRNA, disrupts the dynamic balance of m6A modification, which is perceived as one of the vital reasons for cancer proliferation and cancer metastasis." (PMID 32126149, 2020). "Additionally, METTL3 was commonly highly expressed in most human cancers from TCGA database." (PMID 31230592, 2019). "Significance of these METTL3-regulated phenotypes in women’s cancer remains unknown." (PMID 31426393, 2019). "Furthermore, METTL3 plays a driving role in cancer cell growth, survival and invasion." (PMID 30062093, 2018). "Notably, AML is one of the cancers with the highest levels of both METTL3 and METTL14 expression (data from the Cancer Genome Atlas, TCGA) and, more importantly, METTL3 and METTL14 were found overexpressed in AML cells compared to normal haematopoietic progenitors." (PMID 30096915, 2018). "METTL3 promotes PDK4 expression and can effectively promote the glycolysis of cancer cells and increase the production of ATP in HCC67." (PMID 41522342, 2026). "This contrasts with our prior work showing METTL3 promotes telomeric R‐loop formation via m6A‐modified TERRA, facilitating homologous recombination (HR) in ALT‐positive cancer cells." (PMID 41457744, 2026). "Recent studies have suggested that METTL3 functions as an oncogene by mediating the m6A modifications of EZH2 and MYC, which contributes to the development of cancers." (PMID 41362669, 2026). "Although further optimization and in vivo validation are required, this approach parallels recent advances in targeting RNA modification machinery, such as METTL3 and FTO, in cancer therapy." (PMID 41496500, 2026). "Researchers have also reported that METTL3-mediated M6A modification can decrease ANGPTL3 mRNA levels and that the inhibitory effects of METTL3 silencing on cancer progression can be partially reversed by ANGPTL3 inhibition." (PMID 41312360, 2025). "METTL3 and hnRNPA2B1 modify and stabilize TERRA, promoting the formation of R-loops essential for HR-mediated telomere maintenance in ALT-positive cancer cells." (PMID 40558832, 2025). "Studies have underscored m6A dysregulation, particularly aberrations in METTL3 and METTL14 levels, across various cancers, including breast, colorectal, liver, and lung cancers." (PMID 40785027, 2025). "Specifically, YTHDF1 and METTL3 have been reported to enhance myeloid-derived suppressor cell proliferation, which in turn inhibits CD8+ T cell function across various cancer types." (PMID 39995977, 2025).
cancer (continued). "Other m6A methyltransferases, such as METTL3 and the METTL3 adaptor protein WTAP, were confirmed to affect cellular and organismal processes during cell differentiation and cancer cell progression in mammalian cells." (PMID 40148982, 2025). "METTL3 was previously shown to be upregulated in PDAC, where it promotes cancer cell proliferation, invasion, and chemoresistance." (PMID 40214229, 2025). "The study supports the potential of METTL3 as a prognostic biomarker in CRC and highlights its involvement in immune modulation and cancer progression." (PMID 40177651, 2025). "In prostate cancer (PCa), METTL3 induces homeobox C6 (HOXC6) m6A modification to stabilize its expression and promote cancer cell proliferation, invasion, migration, stemness, and glycolysis." (PMID 41256854, 2025). "In lung adenocarcinoma (LUAD), m6A modification via METTL3 upregulation and ALKBH5 downregulation increases ENO1 translation, promoting glycolysis and providing energy for cancer cell proliferation." (PMID 39802639, 2025). "LARP4B, upregulated by METTL3-mediated, IGF2BP3-dependent m6A modification, promotes cancer stemness progression and impairs sorafenib efficacy by activating the SPINK1-mediated EGFR pathway." (PMID 41298358, 2025). "RNA modification enzymes, particularly RNA methyltransferases such as METTL3 and demethylases such as FTO, have emerged as promising therapeutic targets for cancer treatment." (PMID 40747121, 2025). "It binds with high efficiency to the METTL3-METTL14 complex and has been shown to impede the migration and self-renewal capacity of cancer stem cells in cellular and murine models of myeloid leukemia." (PMID 41157107, 2025). "Numerous studies show that specific RNA modification factors (such as METTL3, IGF2BP3, and ALKBH5) exhibit abnormal expression in various cancers." (PMID 40867324, 2025). "This tripartite mechanism parallels recent findings in cancer biology, where DDX5 collaborates with METTL3 to regulate m6A-dependent RNA splicing, but represents the first report of such a pathway in viral latency." (PMID 41218081, 2025). "Core enzymes such as METTL3, ALKBH5 and IGF2BP proteins play essential roles not only in cancer but also in normal tissue homeostasis, raising concerns about toxicity and selectivity when targeting these proteins therapeutically." (PMID 41228380, 2025). "Moreover, the encouraging results from METTL3 inhibitors, several of which are currently in early clinical development, along with evidence that combining METTL3 inhibitors with PD-L1 blockade enhances antitumor immune efficacy, offer new avenues for cancer treatment." (PMID 40647517, 2025). "Although METTL3 has been the main focus of research so far, further functional analysis of other METTL family members will be increasingly needed in cancer research." (PMID 40448344, 2025). "To elucidate the reason for the diminished m6A levels in GBC, we evaluated the expression of key m6A regulatory factors (METTL3 and METTL14) in paired cancer and normal tissue samples." (PMID 40785027, 2025). "Suppressing METTL3 and YTHDF1 expression decreases RPN2 levels, which inhibits this pathway and affects both cancer cell proliferation and chemotherapy efficacy." (PMID 39802639, 2025). "Our data indicate that METTL3 controls SLC7A11 transcription through GATA binding protein 3 (GATA3) and H3K27 lysine demethylase 6B (KDM6B), highlighting a potential approach for cancer therapy by disrupting m6A-regulated ferroptosis in cancer cells." (PMID 39800682, 2025). "Low expression of METTL3, while high expression of SLC7A11, reduces the survival rate of cancer patients." (PMID 39800682, 2025).